CLK4 (CDC like kinase 4)
Description:
Dual specificity kinase acting on both serine/threonine and tyrosine-containing substrates. Phosphorylates serine- and arginine-rich (SR) proteins of the spliceosomal complex and may be a constituent of a network of regulatory mechanisms that enable SR proteins to control RNA splicing. Phosphorylates SRSF1 and SRSF3. Required for the regulation of alternative splicing of MAPT/TAU. Regulates the alternative splicing of tissue factor (F3) pre-mRNA in endothelial cells.
Tractability: Small molecule: a structure with a bound ligand is known; a high-quality ligand is known; it belongs to a druggable protein family. PROTAC: ubiquitination databases record sites on it; a small molecule that binds it is known.
Target class: Protein Kinase; Enzyme; CMGC protein kinase group; Kinase; CMGC protein kinase CLK family
Chemical probes: KH-CB19 (high quality), ML105, ML106, ML167, ML197, ML315, MU1210 (high quality), SGC-CLK-1 (high quality), T3-CLK (high quality)
Gene: Protein-coding gene on chromosome 5 (178,602,664 to 178,630,615, reverse strand). Ensembl gene ENSG00000113240.
Subcellular location: Nucleus
Subcellular location (Human Protein Atlas): Actin filaments
Gene Ontology:
Molecular function: protein binding; protein serine/threonine kinase activity; protein tyrosine kinase activity; ATP binding; protein kinase activity; protein serine kinase activity; protein serine/threonine/tyrosine kinase activity
Biological process: regulation of RNA splicing
Cellular component: nucleus
Genetic constraint (gnomAD): Loss-of-function variants: 23 observed, 37.46 expected, observed/expected ratio (o/e) 0.61, 90% interval 0.44 to 0.87. The upper end of that interval is the gene's LOEUF score, 0.87, which puts it in group 3 of 6, group 1 being the genes least tolerant of losing a copy. Missense variants: 356 observed, 471.88 expected, observed/expected ratio (o/e) 0.75, 90% interval 0.69 to 0.82. Synonymous variants: 145 observed, 153.67 expected, observed/expected ratio (o/e) 0.94, 90% interval 0.82 to 1.08.
Homologues: Orthologues: chimpanzee CLK4 (100% identical), guinea pig CLK4 (98% identical), dog CLK4 (98% identical), rabbit CLK4 (98% identical), mouse Clk4 (97% identical), macaque CLK4 (90% identical), pig CLK4 (89% identical), rat Clk4 (89% identical), zebrafish clk4a (62% identical), Drosophila melanogaster mnb (26% identical), Caenorhabditis elegans mbk-1 (23% identical), Caenorhabditis elegans hpk-1 (21% identical), and 2 more. Paralogues in human: CLK1 (79% identical), CLK2 (57% identical), CLK3 (51% identical), DYRK1A (27% identical), DYRK1B (27% identical), DYRK3 (26% identical), DYRK2 (25% identical), DYRK4 (25% identical), HIPK2 (25% identical), HIPK3 (24% identical), HIPK1 (23% identical), HIPK4 (19% identical).
Diseases named in the same sentence as CLK4 in open-access papers:
CLK4 is named in the same sentence as 31 diseases in open-access papers, as found by Europe PMC text mining. Sharing a sentence is not in itself a finding about the gene and the disease. The quoted sentences say what the papers report.
cardiac hypertrophy (3 papers, 2022 to 2025). "CLK4 was downregulated in failed myocardia, and cardiac-specific Clk4 deletion (Clk4-cKO) in mice caused cardiac hypertrophy and dysfunction." (PMID 35907876, 2022). "Together, these results uncover the regulatory role of CLK4 in pathological cardiac hypertrophy and elucidate the underlying mechanisms." (PMID 35907876, 2022). "To explore the mechanism by which Clk4 deficiency led to pathological myocardial hypertrophy and heart failure, we performed a phosphoproteomic assay to screen differentially expressed phosphopeptides/phosphoproteins." (PMID 35907876, 2022). "Thus, the mechanism by which cardiomyocyte-specific loss-of Clk4 leads to cardiac hypertrophy and heart failure might involve a decrease in NEXN phosphorylation." (PMID 35907876, 2022). "CLK4 interacts and phosphorylates NEXN at serine 437, and reduced NEXN phosphorylation is associated with cardiac hypertrophy and dysfunction." (PMID 35907876, 2022). "Cardiac-specific Clk4-knockout mice manifest pathological myocardial hypertrophy with progressive left ventricular systolic dysfunction and heart dilation." (PMID 35907876, 2022). "Third, cardiac-specific Clk4 knockout contributed to pathological myocardial hypertrophy and heart failure." (PMID 35907876, 2022). "Herein, we reveal that CLK4 acts as a key regulator of pathological cardiac hypertrophy and that its direct substrate NEXN might have a critical role in the process." (PMID 35907876, 2022). "Here the authors show that the kinase CLK4 ameliorates cardiac hypertrophy by phosphorylating NEXN." (PMID 35907876, 2022). "In summary, our findings identify CLK4 as a regulator of pathological cardiac hypertrophy and indicate that restoration of CLK4 may act as a potential new therapeutic strategy for heart failure." (PMID 35907876, 2022). "We conclude that CLK4 regulates cardiac function through phosphorylation of NEXN, and its deficiency may lead to pathological cardiac hypertrophy." (PMID 35907876, 2022). "Also, the cardiac hypertrophy in Clk4-cKO mice was indicated by dramatic increases in the expression of fetal cardiac genes such as Nppa, Nppb, and myosin heavy chain 7 (Myh7)." (PMID 35907876, 2022). "Importantly, restoring phosphorylation of NEXN ameliorates myocardial hypertrophy in mice with cardiac-specific Clk4 deletion." (PMID 35907876, 2022). "Moreover, the finding indicated that restoration of CLK4 may act as a novel therapeutic target for treating pathological cardiac hypertrophy." (PMID 37029108, 2023). "Mechanistically, we identified nexilin (NEXN) as the direct target of CLK4 and the reduction of phosphorylated NEXN mediated the development of pathological myocardial hypertrophy and heart failure in Clk4-cKO mice." (PMID 35907876, 2022).
breast carcinoma (2 papers, 2018 to 2025). "CLK4 is a member of the Cdc2-like kinase (CLK4) family, targeting CLK4 inhibits the metastasis and progression of breast cancer." (PMID 39786519, 2025). "We also observed that the splice factor kinase CLK3, but not CLK2 and CLK4, was also induced in hypoxic DU145 prostate, HT29 colon and MCF7 breast cancer cell lines." (PMID 29606096, 2018).
glioblastoma (2 papers, 2023 to 2024). The most malignant astrocytic tumor (WHO grade IV). "Subsequent transcriptome and proteome analyses of patient-derived glioblastoma (GBM) neurospheres treated with 2 revealed that this compound impaired CLK4 interactions with spliceosomal proteins, thereby altering RNA splicing." (PMID 38398225, 2024).
heart failure (2 papers, 2022 to 2023). Inability of the heart to pump blood at an adequate rate to meet tissue metabolic requirements. "Taken together, these findings indicate that Clk4 deficiency-mediated heart failure may be caused primarily by decreased NEXN phosphorylation." (PMID 35907876, 2022). "First, our results obtained in two models of heart failure indicate that the CLK4 protein is downregulated in the myocardium, yet how CLK4 is regulated in these settings remains to be further investigated." (PMID 35907876, 2022). "CLK4 is a potential intervention target for the prevention and treatment of heart failure." (PMID 35907876, 2022). "Similarly, heart weight-to-body weight ratio, as well as heart weight to-tibial length ratio, were significantly greater in Clk4-cKO mice, and the lung weight-to-body weight ratio, an indirect indicator of heart failure, were also increased notably in Clk4-cKO mice." (PMID 35907876, 2022). "Here, we show that CDC-like kinase 4 (CLK4) is a critical regulator of cardiomyocyte hypertrophy and heart failure." (PMID 35907876, 2022).
lung carcinoma (2 papers, 2021 to 2025). "The kinase screening also revealed a low remaining activity for CLK1 and CLK4, to our best knowledge, two kinases which have not been linked to lung cancer." (PMID 33435251, 2021).
pancreatic cancer (2 papers, 2025). "Cdc‐like kinase 4 (CLK4), a kinase that regulates alternative splicing by phosphorylating spliceosome components, is implicated in aberrant splicing events driving pancreatic cancer progression." (PMID 40126184, 2025). "In this study, we identified a novel therapeutic inhibitor targeting the critical splicing regulatory kinase CLK4 for treating pancreatic cancer." (PMID 40126184, 2025). "Researchers established a computational model integrating CLK4 inhibitor pharmacology and identified the novel specific CLK4 inhibitor compound 150441, which significantly inhibits pancreatic cancer cell growth and survival in cell models." (PMID 41463025, 2025). "Our study elucidates the application of the SBVS approach in developing novel CLK4 inhibitors and provides a therapeutic strategy for targeting RNA splicing in pancreatic cancer treatment." (PMID 40126184, 2025). "In summary, this study identified a novel inhibitor that serves as a crucial starting point for developing potent CLK4 inhibitors for treating pancreatic cancer." (PMID 40126184, 2025). "First, CLK4 inhibition allows for selective modulation of gene expression, enabling precise regulation of oncogenes and tumor suppressor genes in pancreatic cancer." (PMID 40126184, 2025). "CLK4 drives pancreatic cancer progression by phosphorylating the spliceosome." (PMID 41463025, 2025). "CLK4 represents a promising therapeutic target for the treatment of pancreatic cancer." (PMID 40126184, 2025).
brain cancer (1 paper, 2022). A primary or metastatic malignant neoplasm affecting the brain. "S5B), analysis of the GlioVis Chinese Glioma Genome Atlas (CGGA) dataset shows a significant association of higher expression of CLK2, but not CLK1, CLK3, or CLK4, with poor OS, and CLK2 mRNA expression significantly increases with grade in multiple brain cancers, including GBM." (PMID 35731869, 2022).
breast tumor (1 paper, 2025). "Interestingly, CLK1 and CLK4 mRNA expression levels were significantly lower in breast tumor-to-normal and TNBC-to-ER positive comparisons." (PMID 40731028, 2025).
viral infection (1 paper, 2016). "Among the differential ASEs associated with viral infection, at least 10 ASEs resulted in the addition or loss of predicted nuclear localization signals (NLS) including the CDC-Like Kinase 4 (CLK4), the e2F3 transcription factor, and the Influenza Virus NS1A Binding Protein (IVNS1ABP)." (PMID 27598998, 2016).
cancer (5 papers, 2021 to 2025). A tumor composed of atypical neoplastic, often pleomorphic cells that invade other tissues. "CLK4 regulates mRNA splicing by phosphorylating SR proteins, and dysregulation of this process contributes to cancer progression." (PMID 40126184, 2025). "It selectively inhibits CLK4, suppresses cancer cell growth, induces G2/M arrest, and alters RNA splicing, highlighting its therapeutic potential." (PMID 40126184, 2025). "Despite the significance of CLK-4 in neurodegenerative disease and cancer-related drug discovery research, it appears that only limited number of earlier computer-aided molecular design and discovery efforts dealing with CLK4 inhibitors were reported." (PMID 35424985, 2022). "Cdc2-like kinase 4 (CLK4) inhibitors are of potential therapeutic value in many diseases particularly cancer." (PMID 35424985, 2022). "CLK4 regulates alternative splicing, contributing to cancer progression." (PMID 40126184, 2025). "Therefore, there is a need to develop a new CLK4 inhibitor with high selectivity for cancer treatment through targeting the aberrant AS." (PMID 40126184, 2025). "Inhibiting CLK4 can modulate mRNA splicing and potentially inhibit cancer growth." (PMID 40126184, 2025).
tumor (2 papers, 2022 to 2023). "And function enrichment of the top 550 genes in either group implies that CLK4 level is possibly related to tumor metabolism reprogramming (the third enriched pathway)." (PMID 35092699, 2022). "It was observed that the reintroduction of CLK4‐M307Q in CLK4 knockdown ESCC cells significantly enhanced cell proliferation and tumor growth in xenograft experiments as compared with the CLK4‐M307T group." (PMID 35092699, 2022). "CLK4 level was lower in ESCC tissues than that in non‐tumor samples." (PMID 35092699, 2022). "In this study, we reveal a novel action mechanism of CLK4 in ESCC as a tumor inhibitor." (PMID 35092699, 2022).
CLK4 also shares sentences with these, for which no sentence is quoted: neurodegenerative disease (2 papers); Alzheimer disease (1); esophageal carcinoma (1); esophageal squamous cell carcinoma (1); Fanconi anemia (1); gastric cancer (1); glioma (1); heart disease (1); hypertrophy (1); immune diseases (1); leukemia (1); lung squamous cell carcinoma (1); metabolic disorders (1); neurological diseases (1); paraganglioma (1); pheochromocytoma (1); prostate carcinoma (1); theileriasis (1); thyroid carcinoma (1); uterine corpus endometrial carcinoma (1).